MSH3 (mutS homolog 3)
Diseases named in the same sentence as MSH3 in open-access papers (continued):
Sharing a sentence is not in itself a finding about the gene and the disease.
tumor (continued). "Regarding MSH3, only 7 of 488 (1.4%) tumours showed reduced expression, 79 (16.2%) showed moderate expression, and 402 (82.4%) showed strong expression." (PMID 35099128, 2022). "MSH3 mRNA expression levels vary greatly in the TCGA colorectal cohort but can be considered low in 17% (87/524) of the tumours, when compared with the mean expression in normal tissue specimens." (PMID 34298744, 2021). "About 41% (39/96) of the tumours displayed at least a 2-fold reduction in MSH3 transcript levels compared to matching normal tissue; of these, 13% (12/96) showed >4-fold reduction." (PMID 34298744, 2021). "Regions that encode gene products (proteins) involved in tumor suppression (e.g., TGFBR2), cellular growth, DNA repair (e.g., MSH3, MSH6), and apoptosis (e.g., BAX) contain repeat sequences, and genetic changes are likely to occur in these regions." (PMID 34185173, 2021). "While immunohistochemical staining showed conserved MSH3 nuclear expression in normal and tumor tissue from case 74, tetranucleotide repeats analysis displayed instability in two out of six microsatellites, indicating EMAST." (PMID 32635641, 2020). "Significant associations were also observed for MSH3 rs26279, MSH4 rs5745325, NBN rs1805794, and tumor histotype." (PMID 32957448, 2020). "Validated variants showed that the tumor suppressor genes APC and ARID1 and the DNA MMR genes MSH3 and MSH6 are the genes with the highest numbers of validated variants." (PMID 31080553, 2019). "Subsequently, tumors and matched non-tumor tissues were subjected to panel sequencing that revealed de novo somatic frameshift mutations in homopolymer regions of several genes including MSH3 and MLH3, confirming a defect in MMR in the tumor tissue." (PMID 31659152, 2019). "Tumor sections were stained for MSH3, and staining intensity was evaluated via the Histoscore (H-score)." (PMID 30532127, 2018). "Our study findings have implications for the treatment of CRC depending upon MSH3 status in the tumor." (PMID 23724141, 2013). "MSH3-deficient mice develop late onset MSI-positive gastrointestinal cancer, suggesting that MSH3 deficiency can contribute to tumor initiation." (PMID 23724141, 2013). "First, when MSH3(-1) mRNA is degraded very fast, our observed sensitivity of endogenously MSH3(-1) expressing tumor cells towards specific T cells implies that the described epitopes must be very immunogenic and the raised T cells must be of high avidity." (PMID 22110587, 2011). "Our results show that several MSH3(-1) epitopes can be recognized on tumor cells following natural expression and proteasomal processing." (PMID 22110587, 2011). "Many of these genes identified by loss of heterozygosity and allele-specific expression are known or putative tumor suppressor genes, such as BRCA1, MSH3 and SETX, which participate in DNA repair pathways." (PMID 21108794, 2010). "LOH on 9p was significantly associated with LOH on 5q, and tumours demonstrating LOH at both the CDKN2 (9p21) and MSH3 (5q11-q12) genes had a significantly higher fractional allele loss than those retaining heterozygosity at these sites." (PMID 9764589, 1998). "The tumour from patient I_26197, a carrier of an MLH1 germline variant, exhibited microsatellite instability, a higher number of missense variants, and had a mutation in MSH3, which also belongs to the mismatch repair pathway (MMR)." (PMID 40446793, 2025). "In addition, variants in MMR pathway genes, MSH3, MSH6, LIG1, MCM9, and POLD3, were associated with relatively high MSI score and/or high mutational burden in 6 tumor samples." (PMID 41353477, 2025). "Tissue immunohistochemical staining for MSH3 demonstrated variant MSH3 protein is present in the cytoplasm and cell membrane but not in the nucleus of normal and tumor epithelial cells." (PMID 38243056, 2024).
tumor (continued). "These plots show a WT reference allele (0 peak, in beige), representing WT tumor alleles plus stromal admixture, and several contracted or expanded tumor alleles depending on MSH6/MSH3 homopolymer mutation within a sample on either side of the reference allele count (workflow)." (PMID 38956208, 2024). "In addition, the patient’s tumor had mutations in genes that are associated with genetic instability, including a CHEK2 mutation and VUSs in MSH3, and MUTYH." (PMID 37202426, 2023). "When synthesized in a di-valent scaffold, siRNA-mediated silencing of Msh3 effectively blocked CAG-repeat expansion in the striatum of two HD mouse models without affecting tumor-associated microsatellite instability or mRNA expression of other MMR genes." (PMID 37177784, 2023). "Given the functional mechanism of MSH3, MSH3 deficient tumours are expected to show neither an increased, hypermutated rate of SBS, nor any specific type of SBS." (PMID 34843512, 2021). "Our data and the TCGA data indicate that tumour levels of MSH3 mRNA expression vary greatly." (PMID 34298744, 2021). "MSH3 dysfunction is a potential contributory pathway toward neoplasia in UC that could be targeted by therapeutic intervention." (PMID 31789935, 2019). "Investigating MMR gene mutations and methylation status in MSI tumor samples, we only observed few cases of MSH6 (MutSα), MSH3 (MutSβ), PMS2 (MutLα), PMS1 (MutLβ), and MLH3 (MutLγ) high-impact mutations often in combination with inactivation of other MMR genes." (PMID 29636374, 2018). "The majority of mCRC patients (n = 381, 69.4%) had a high expression of MSH3 in tumor cells." (PMID 25884216, 2015). "The peripheric portion of the tumor presented a different profile: 5/84 CpG sites were aberrantly methylated, from which 2 sites were shared with the center portion, that is, MSH3 and MLH1, and 3 sites were exclusively methylated in the tumor periphery, that is, MSH6, MGMT, and APC." (PMID 25544907, 2014). "Here we studied the effect of permanent MSH3 silencing to test whether this alters cellular pathways which may affect tumor development." (PMID 23209772, 2012). "These antigenic epitopes could be good candidates for immunotherapy, because mutations in the MSH3 gene, along with others, e.g. TGFβRII, BAX and MSH6, appear to play an active role in tumor progression." (PMID 22110587, 2011). "Our results are clinically relevant emphasising the importance of MSH3 in dinucleotide loop repair and we encourage performing MSH3 mutation analysis when a tumour shows dinucleotide but no mononucleotide repeat instability." (PMID 20160730, 2010). "The finding is clinically relevant because the strong role of MutSβ in IDL2 repair indicates MSH3 deficiency in tumours with low dinucleotide and no mononucleotide repeat instability." (PMID 20160730, 2010). "Further studies are needed to determine whether loss of MSH6 in some tumor cells is mechanistically related to the expression of variant MSH3 or not." (PMID 38243056, 2024). "Furthermore, immunohistochemical analysis showed an almost complete absence of MSH3 protein in cells, and a complete loss of its presence in the nucleus in both normal and tumor tissues of these individuals." (PMID 37510378, 2023). "Meanwhile, it has been reported that MSH3 deficiency is associated with EMAST and with low levels of instability at dinucleotide repeat loci, and MSH3 deficiency may elevate susceptibility to certain neoplastic diseases and contribute to tumor initiation." (PMID 25927356, 2015). "Genes involved in tumor suppression (e.g., TGFBR2), cell proliferation, DNA repair (e.g., MSH3, MSH6), and apoptosis (e.g., BAX) contain these repetitive sequences in the coding regions, where alterations tend to develop." (PMID 41214301, 2026).
tumor (continued). "Some genes containing these repetitive sequences code for proteins involved in tumor suppression (e.g., TGFBR2), cellular proliferation, DNA repair (e.g., MSH3, MSH6), and apoptosis (e.g., BAX)." (PMID 41214301, 2026). "Unique molecular characteristics have been described in neoplasms from defective DNA repair-related polyposis involving the MUTYH, NTHL1, MBD4, MSH3, POLE and POLD1 genes and the MMR genes in CMMRD." (PMID 40237887, 2025). "Further exploratory studies of MSH3, EMAST, KRAS and immune cell infiltration in the tumour microenvironment are indicated in SA CRC patients." (PMID 36280820, 2022). "Dysfunctional MSH3 has shown to lead to MSI, appearing to be inflammation-related within the tumour microenvironment." (PMID 36280820, 2022). "The genes involved in tumor suppression (e.g., TGFBR2), cell proliferation, DNA repair (e.g., MSH3 and MSH6), apoptosis (e.g., BAX), etc., contain repetitive sequences in the coding regions, and alterations tend to develop in these regions." (PMID 34185173, 2021). "To analyze, if the observed reactivity against MSH3(-1)-derived peptides was confined to peptide-loaded target cells, killing activity towards MSI+ tumor cells was examined." (PMID 22110587, 2011). "Contrary to that it would secondly raise concerns about the potential of MSH3(-1) protein to be cross-presented by professional antigen-presenting cells and thus would substantially limit it's usefulness as MSI-specific tumor antigen." (PMID 22110587, 2011). "LOH on 5q occurred at the sites of the MSH3 mismatch repair gene and the APC tumour-suppressor gene." (PMID 9764589, 1998). "Of note, the only RASGRF fusion we identified in a PDAC with a concurrent KRAS mutation is MSH3-RASGRF2 (which lacks the PH1 but not DH domain), suggesting the fusion is unlikely to be an oncogenic driver in that tumor." (PMID 40615519, 2025). "Since frameshift peptides are a driving force of efficient checkpoint immune therapy, the expected higher number of indels in MSH3-related CRC might result in a benefit, but the effect would probably be lower than in classic MSI tumours." (PMID 34843512, 2021). "EMAST is a biomarker for MSH3 dysfunction; it does not necessary mean that EMAST itself is causal for progression of neoplasia." (PMID 31789935, 2019). "Methylation frequency of the mutS homolog 3 (MSH3) gene promoter was significantly higher in tumor samples from smokers compared to tumor samples from non-smokers." (PMID 27110300, 2016). "According to our in vitro studies MSH3-silencing does not alter the proteome in favor of tumor growth, invasion, or metastasis." (PMID 23209772, 2012). "Selected CRC target genes involved in apoptosis (BAX), tumor growth (TGFβRII), WNT pathway (AXIN2, TCF4, WISP3), DNA repair (ATM, ATR, BLM, BRCA1, BRCA2, DNAPKcs, MBD4, MRE11, MSH3, MSH6, RAD50, XRCC2) and PI3-kinase signaling (PTEN) were analyzed for mutations in MSI-positive HGG samples." (PMID 21637783, 2011). "On the other hand, some MSI-L or even MSI-H (if two markers of the Bethesda panel are affected) tumors may in fact have only dinucleotide frameshifts, a defect which can be indicative of isolated MSH3 dysfunction, and thus share more similarities with EMAST than the MSI tumor phenotype." (PMID 37510378, 2023).
tumor (continued). "In addition, there is functional compensation between MMR proteins (PMS2/PMS1, MSH6/MSH3), which can maintain the tumor MSS status in the absence of the four most frequently detected MMR proteins." (PMID 36591511, 2022). "Additionally, tumor evolution might in different tumor phases favor a subset of cells in which MSH3 is no longer present or relevant." (PMID 37510378, 2023). "The distribution of these three MSH3 expression groups was not statistically significantly different among the EMAST (2+) or EMAST (3+) and EMAST‐negative tumours (p = 0.092 and p = 0.072, respectively)." (PMID 35099128, 2022). "Again, this is consistent with isolated MSH3 dysfunction, and the frequency of EMAST among UC-derived CRCs was significantly higher than the frequency among UC samples without neoplasia (P = 0.0045), suggesting progressive accumulation of frameshifts with advancing tumorigenesis." (PMID 31789935, 2019).
infection (5 papers, 2012 to 2023). The state of being infected such as from the introduction of a foreign agent such as serum, vaccine, antigenic substance or organism.
neurodegenerative disease (4 papers, 2017 to 2025). A disorder of the central nervous system characterized by gradual and progressive loss of neural tissue and neurologic function. "The MSH3 gene has been implicated in multiple biological processes, including cancer development, neurodegenerative diseases, and genomic stability." (PMID 40508992, 2025).
gastrointestinal tumors (2 papers, 2012 to 2023).
MSH3 also shares sentences with these, for which no sentence is quoted: myotonic dystrophy type 1 (4 papers); Fanconi anemia (3); head and neck squamous cell carcinoma (3); hepatocellular carcinoma (3); bladder cancer (2); bladder tumors (2); Brain atrophy (2); colon adenoma (2); colorectal (2); hereditary non-polyposis colorectal cancer (2); metastatic disease (2); promyelocytic leukaemia (2); ulcerative colitis (2); acute stress disorder (1); adenoid cystic carcinoma (1); Atrophy (1); B-cell lymphoma (1); benign tumors (1); cholangiocarcinoma (1); CMMRD syndrome (1); Cognitive impairment (1); colon adenocarcinoma (1); Cowden disease (1); Crohn disease (1); developmental delay (1); fragile X syndrome (1); genetic diseases (1); glioma (1); hematologic malignancies (1); hereditary colorectal cancer (1).
A further 20 diseases each share a sentence with MSH3 in 1 paper.